UHMK1 (U2AF homology motif kinase 1)
Diseases named in the same sentence as UHMK1 in open-access papers (continued):
Sharing a sentence is not in itself a finding about the gene and the disease.
cancer (12 papers, 2017 to 2025). A tumor composed of atypical neoplastic, often pleomorphic cells that invade other tissues. "Dysregulation or mutations in UHMK1 have been indicated as a high-penetrance factor in human cancers of pancreatic, ovarian, or gastric origin." (PMID 35151311, 2022). "UHMK1 dysregulation or mutation represents a high-penetrance factor implicated in diverse cancers." (PMID 40918462, 2025). "UHMK1 has been recognized as a critical downstream effector of many signaling pathways that drive cancer proliferation and invasion." (PMID 40918462, 2025). "In these different cancer types, elevated expression levels of UHMK1 promote the proliferation of cancer cells." (PMID 38287425, 2024). "The abnormally elevated UHMK1 has been reported to be a potential oncogenic factor in different types of human cancers." (PMID 35501324, 2022). "Our discovery that NRF3 promotes cancer cell proliferation by inducing the UHMK1 gene expression is a first report of physiological role of NRF3 in cancer." (PMID 28970512, 2017). "NRF3 promotes cancer cell proliferation by inducing the gene expression of the cell cycle regulator UHMK1." (PMID 28970512, 2017). "Given that UHMK1 induces the proliferation and cell cycle progression of cancer cells, our findings gave rise to the next important question: whether NRF3 knockdown reduces cell proliferation." (PMID 28970512, 2017). "In conclusion, our findings demonstrate that UHMK1 is overexpressed in CRC, as in other cancer types." (PMID 35501324, 2022). "Thus, we are the first to propose a new UHMK1/STAT3 positive feedback loop to augment JAK/STAT3 signaling and lead to cancer development and progression." (PMID 35501324, 2022).
tumor (12 papers, 2011 to 2025). "Collectively, these findings establish UHMK1 overexpression in PCa as a feature linked to tumor malignancy." (PMID 40918462, 2025). "Functional studies showed that UHMK1 depletion suppressed tumor cell proliferation and metastasis, while its overexpression promoted these processes." (PMID 40918462, 2025). "U2AF homology motif kinase 1 (UHMK1) has been associated with RNA processing and protein phosphorylation, thereby influencing tumor progression." (PMID 40918462, 2025). "UHMK1 expression was enhanced in PDAC, and high UHMK1 expression correlated with tumor stage, and lower overall survival." (PMID 35359403, 2022). "A recent study showed that EBLN3P promotes tumor development via targeting miR-323a-3p/UHMK1 in CRC." (PMID 35501324, 2022). "To evaluate the effect of UHMK1 on tumor growth, we lipotransfected MIA-PaCa2 cells with siH19, siUHMK1, or a control siRNA construct followed by xenotransplantation to the CAM of fertilized chicken eggs at day 9 of chick development." (PMID 35359403, 2022). "The essential role of UHMK1 for cell proliferation was further confirmed in subcutaneous xenograft tumor models." (PMID 35501324, 2022). "Consistently, EdU assay and in vivo subcutaneous tumor xenograft assay also confirmed that UHMK1 overexpression promoted CRC cell proliferation and played a crucial role in tumor growth." (PMID 35501324, 2022). "Although the biological function of UHMK1 remains largely unclear, its dysregulated expression in tumor specimens and potential regulatory effects on tumor progression have been frequently reported." (PMID 34109193, 2021). "EBLN3P is an oncogenic lncRNA facilitating CRC tumor formation through the way of being one ceRNA regulating UHMK1's expressing state via sponging miR-323a-3p." (PMID 34109193, 2021). "UHMK1 expression was distinctly increased in CRC specimens in comparison with non-tumor tissues by analyzing TCGA datasets." (PMID 34109193, 2021). "Statistically significant associations were identified for lymph node metastasis (12 genes and three miRNAs), tumor size (eight genes and one miRNA) and perineural invasion (UHMK1 gene) (P < 0.01, FDR < 20%)." (PMID 28122331, 2017). "Crucially, UHMK1 expression was strongly associated with Gleason score, tumor stage, and lymph node metastasis status, but not patient age." (PMID 40918462, 2025). "Furthermore, we demonstrated that UHMK1 upregulation in PCa significantly enhanced tumor growth and dissemination." (PMID 40918462, 2025). "siRNA-mediated downregulation of H19 or UHMK1 inhibited tumor proliferation and xenograft growth." (PMID 35359403, 2022). "Because nomograms are widely used in oncology to predict personalized prognosis and treatment, we added the obtained UHMK1 expression data to a nomogram, containing the confirmed prognostic factors of “age”, “tumor grade”, and “radiation therapy”, which were obtained from TCGA online database." (PMID 35359403, 2022). "Moreover, in melanoma, UHMK1 inhibits tumor cell death by reprogramming mitochondrial metabolism." (PMID 40918462, 2025). "Collectively, our results indicate the existence of a positive feedback loop between UHMK1 and MTHFD2, sustaining continuous activation of this signaling pathway and facilitating tumor progression." (PMID 40918462, 2025). "On the contrary, UHMK1 upregulation significantly promoted CRC cell line proliferation and in vivo tumor growth." (PMID 35501324, 2022). "The loss of COX5B-mediated facilitation of bioenergy production resulted in AMPK activation, leading to repression of UHMK1 (an oncogene) expression and induction of ULK1 (a tumor suppressor) via unidentified mechanisms." (PMID 32580279, 2020). "One may speculate that a complete knockout of UHMK1 or H19, e.g. by the use of CRISPR/Cas would have resulted in an even more pronounced inhibition of tumor xenograft growth." (PMID 35359403, 2022).
tumor (continued). "Moreover, we proved for the first time that UHMK1 downregulation restrained CRC cell proliferation and tumor growth." (PMID 35501324, 2022). "To define the role of UHMK1, we assessed the mRNA and protein levels of UHMK1 in PDAC and other tumor entities as well as in nonmalignant pancreatic tissues." (PMID 35359403, 2022).
psychiatric diseases (2 papers, 2012 to 2021). "Interestingly, some genes (such as YWHAH and UHMK1) are genes with functional roles in neurodevelopment and other psychiatric diseases." (PMID 32327736, 2021).
UHMK1 also shares sentences with these, for which no sentence is quoted: liver cancer (3 papers); atherosclerosis (1); Azoospermia (1); breast invasive carcinoma (1); cervical squamous cell carcinoma (1); cholangiocarcinoma (1); diffuse large B-cell lymphoma (1); endocervical adenocarcinoma (1); esophageal carcinoma (1); liver failure (1); lung adenocarcinoma (1); lung adenoma (1); lung carcinoma (1); lymphoid neoplasm (1); skin cutaneous melanoma (1); stomach adenocarcinoma (1); thymoma (1).